RNU6-380P (RNA, U6 small nuclear 380, pseudogene)
Gene: Small nuclear RNA gene on chromosome 15 (80,663,772 to 80,663,878, forward strand). Ensembl gene ENSG00000222139.
Homologues: Orthologues: chimpanzee U6 (99% identical), macaque U6 (91% identical), dog U6 (76% identical). Paralogues in human: RNU6-1050P (82% identical), RNU6-1309P (82% identical), RNU6-1209P (81% identical), RNU6-1243P (81% identical), RNU6-238P (81% identical), RNU6-744P (81% identical), RNU6-944P (81% identical), RNU6-255P (80% identical), RNU6-336P (80% identical), RNU6-543P (80% identical), RNU6-703P (80% identical), RNU6-98P (80% identical), and 1285 more.